CYP2B6 (cytochrome P450 family 2 subfamily B member 6)
Diseases named in the same sentence as CYP2B6 in open-access papers (continued):
Sharing a sentence is not in itself a finding about the gene and the disease.
hepatocellular carcinoma (11 papers, 2016 to 2022). A malignant tumor that arises from hepatocytes. "It was previously reported that CYP2B6 mRNA expression was decreased in hepatocellular carcinoma (HCC), and contrary, significantly increased in HBV and alcoholic cirrhosis, as well as in NAFLD." (PMID 34117631, 2021). "Conversely, the progression of NAFLD to hepatocellular carcinoma drastically decreased the estimated activity of CYP2B6 in hepatocellular carcinoma patients." (PMID 32155178, 2020). "There was not significant correlation between the expression of CYP2B6 and prognosis of hepatocellular carcinoma, while CYP2C9 and CYP3A4 genes were significantly downregulated and correlated with poor prognosis in hepatocellular carcinoma." (PMID 35078445, 2022). "When we merged these hub genes with differentially expressed genes in GSE14520 dataset and differentially expressed genes of hepatocellular carcinoma in GEPIA database, seven communal genes were found, they were AURKA, CDK1, CCNB1, TOP2A, CYP3A4, CYP2C9, and CYP2B6." (PMID 35078445, 2022). "When hepatoma cells were treated with IL-6, the levels of CYP1A1, CYP1A2, CYP2B6, CYP3A3, and CYP3A4 mRNAs were markedly suppressed, as well as activities of CYP1A2, CYP2B6, and CYP3A4." (PMID 35185562, 2022).
steatosis (10 papers, 2009 to 2025). Increased lipid within the cytoplasm of cells. "Previous research demonstrated that there are several oxylipins produced directly by human CYP2B6 and some of these oxylipins are associated with high-fat diet mediated steatosis, such as 9-HODE, 14,15-EET, PGF2a, and 13-KODE." (PMID 38393201, 2024). "We assessed hepatic fibrosis and steatosis by transient elastography and CYP2B6 alleles, principally responsible for methadone metabolism." (PMID 32302325, 2020). "Overall, our data is consistent with CYP2B6 expression leading to increased oxylipins that are associated with increased PPARγ activity and improved glucose sensitivity at the cost of increased steatosis." (PMID 36520866, 2022). "Differences observed between the oxylipin-treated and hCYP2B6-Tg mice would be interpreted as evidence that other factors besides these oxylipins are driving CYP2B6-mediated steatosis." (PMID 40002708, 2025). "The experimental results showed that overexpression of CYP2C11 and CYP2B6 alleviated hepatic lipid accumulation and reversed steatosis in the AM group." (PMID 40433307, 2025). "CYP2B6 is the only human detoxification CYP whose loss is associated with obesity, and Cyp2b-null mice show greater diet-induced obesity with increased steatosis than wildtype mice." (PMID 36520866, 2022). "Given that 9-HODE and 9-HOTrE are preferentially produced by CYP2B6 and alter hepatic lipid accumulation and gene expression in vitro, we hypothesized that these oxylipins are contributing to the increased steatosis seen in hCYP2B6-Tg mice." (PMID 40002708, 2025). "We used a fasting protocol to study the role of CYP2B6, 9-HODE, and 9-HOTrE in steatosis." (PMID 40002708, 2025).
depression (9 papers, 2012 to 2025). "Since efavirenz is predominantly detoxified by the CYP2B6, therefore, patients may be at increased risk for toxicity such as depression and suicidal tendencies with some CYP2B6 genetic variants, reducing the function of CYP2B6." (PMID 35250581, 2022). "Serious toxic effects of efavirenz, for example, depression and suicidal tendencies, can be optimized by adjusting the dose based on CYP2B6 genotyping results of patients." (PMID 35250581, 2022). "However, as the evidence grows, institutions could implement panels that include CYP2B6 and other relevant genes for patients likely to receive ketamine (for pain or depression)." (PMID 40981114, 2025). "Furthermore, bupropion is metabolized by CYP2B6 and is prescribed to depression patients who have other psychiatric comorbidities such as attention deficit hyperactivity or substance use disorders, which may contribute to a higher baseline risk of adverse events." (PMID 40572791, 2025). "However, Val66Met and CYP2B6 did not significantly predict changes in symptoms of depression, suicide, anxiety, or average dissociation." (PMID 38477185, 2024).
epilepsy (8 papers, 2016 to 2025). A brain disorder characterized by episodes of abnormally increased neuronal discharge resulting in transient episodes of sensory or motor neurological dysfunction, or psychic dysfunction. "People who are homozygous for the CYP2B6 516T/T genotype, which is associated with poor efavirenz clearance, are more at risk of efavirenz-induced seizure disorder." (PMID 27072009, 2016). "In contrast, the CYP2B6 *1/*2 and *2/*2 genotypes were identified in 42% of patients with drug-resistant epilepsy who did respond to CBD treatment." (PMID 40918507, 2025). "The most significant differences regarding SNP rs8192709 in CYP2B6 were observed in two specific subgroups of patients with epilepsy of unknown etiology." (PMID 40918507, 2025). "The anticonvulsant CBZ is widely prescribed in the long-term therapy of epilepsy and is a potent inducer of CYP3A4 and CYP2B6." (PMID 36559144, 2022). "The anticonvulsant carbamazepine is frequently used in the long-term therapy of epilepsy and is a known substrate and inducer of cytochrome P450 (CYP) 3A4 and CYP2B6." (PMID 33671323, 2021). "Furthermore, CYP2B6 together with CYP3A4 are central to the metabolism of clobazam, a common anti-seizure medication used in the treatment of many forms of epilepsy." (PMID 33096940, 2020). "Furthermore, CYP2B6 and CYP3A4, the human homologues of Cyp2b10 and Cyp3a11 (another CYP induced in this study), are central in the metabolism (N-demethylation) of clobazam, an anti-seizure medication used in the treatment of epilepsy." (PMID 31052254, 2019).
tuberculosis (8 papers, 2011 to 2025). A chronic, recurrent infection caused by the bacterium Mycobacterium tuberculosis. "Our result indicates that the extent of efavirenz auto-induction is influenced by population differences, CYP2B6 genotype, and anti-tuberculosis co-treatment." (PMID 32116703, 2020). "In conclusion, after 16 weeks of treatment, efavirenz clearance is comparable between HIV and HIV/Tuberculosis patients with the same CYP2B6 genotype." (PMID 30397233, 2018). "Hence concomitant uses of these drugs exacerbate the incidence of DILI, ii) anti-tuberculosis drugs mainly rifampicin induces CYP2B6 and CYP3A5 lowering efavirenz plasma concentration while isoniazid inhibits some CYP enzymes." (PMID 22162992, 2011). "The impact of anti-tuberculosis co-treatment on efavirenz (EFV) exposure is still uncertain as contradictory reports exist, and the relevance of CYP2B6*6 genetic polymorphism on efavirenz clearance while on-and-off anti-tuberculosis co-treatment is not well investigated." (PMID 30397233, 2018). "Among subjects with the same CYP2B6 genotypes, efavirenz clearances were comparable between HIV and HIV/Tuberculosis subjects." (PMID 30397233, 2018). "Similar CYP2B6 genotype-based efavirenz dose recommendations regardless of rifampicin-based anti-tuberculosis co-treatment for sub-Saharan Africa population have been published recently." (PMID 30397233, 2018). "CYP2B6 genotyping but not anti-tuberculosis co-treatment should guide efavirenz dosing to optimize treatment outcomes." (PMID 30397233, 2018). "Comparisons of CYP2B6, CYP3A5, NAT2, SLCO1B1 and ABCB1 variant alleles and genotype/haplotypes between DILI non-DILI cases among HIV patients with or without tuberculosis." (PMID 22808112, 2012).
type 2 diabetes (8 papers, 2017 to 2025). "One study using a cocktail approach showed that CYP2B6, CYP2C19 and CYP3A activity decreased, CYP1A2 and CYP2C9 activity increased, and CYP2D6 and CYP2E1 activity was unaffected in type II diabetes (T2D)." (PMID 34867341, 2021). "Type 2 Diabetes (T2D) alters CYP activities in an isoform-dependent manner: CYP2C19, CYP2B6, and CYP3A4 activities are reduced by 1.5–2-fold, whereas other isoforms may be unaffected or slightly increased." (PMID 41158125, 2025). "Hence, the present study aims to characterize the activity of CYP1A2, CYP2B6, CYP2C9, CYP2C19, CYP2D6, CYP3A4/5, and P-glycoprotein (P-gp) pump in patients with type 2 diabetes (T2DM)." (PMID 32337164, 2020).
liver cancer (7 papers, 2011 to 2024). An epithelial or non-epithelial malignant neoplasm that arises from the liver. "In our analysis, CYP2B6 and CYP2C19 were discovered to be upregulated in HCC, and the roles in the process of liver cancer are required to be further verified." (PMID 34423049, 2021).
nicotine dependence (7 papers, 2011 to 2022). Physical and psychological dependence on nicotine. "In that study, we reported that genetic variants of the drug transporter ABCB1 and a particular haplotype (1236TT-2677TT-3435TT) were significantly associated with non-smoking status, while no other associations with genetic variants of ABCB1 or CYP2A6, CYP2B6 with nicotine addiction was found." (PMID 35222535, 2022). "Genome-wide association studies have identified single nucleotide polymorphisms (SNPs) as risk factors for nicotine dependence and lung cancer in genes encoding nAChR subunits (CHRNB3-CHRNA6 and CHRNB4-CHRNA3-CHRNA5 clusters), and in nicotine-metabolizing enzymes (CYP2A6 and CYP2B6)." (PMID 26623516, 2015). "The expression of CYP2B6 in the brain might be related to a role in nicotine dependence." (PMID 33329709, 2020).
co-infection (6 papers, 2013 to 2023). "In conclusion, this study highlights the significant increase in CYP2B6 gene expression associated with co-infection, a significant association of the presence of HIV infection with the increase in CYP3A4 mRNA levels, and a trend observed for the downregulation of ABCB1 in patients using lamivudine." (PMID 37512019, 2023). "In addition to these findings, the presence of HIV/HCV co-infection independently correlated (p < 0.05) with the increased expression of genes encoding CYP2B6." (PMID 37512019, 2023). "This study is one of the few that have examined efavirenz related neuropsychiatric toxicity during rifampicin treatment in an African context where HIV/TB co-infection and CYP2B6 genetic variation are most prevalent." (PMID 23734829, 2013). "Thus, a prospective clinical efficacy study that incorporates efavirenz PK parameters, as well as medication adherence and CYP2B6 genotypes in a predictive model for virologic response, is needed to inform strategies to optimize efavirenz-based ART in children with TB/HIV coinfection." (PMID 30397066, 2019).
hemorrhagic cystitis (6 papers, 2012 to 2025). Inflammation of the bladder resulting in bloody urine. "Most CYC-related genetic variations are associated with ADR, such as the higher risk of hemorrhagic cystitis and leukopenia associated with CYP2B6 and GST gene polymorphism." (PMID 35935867, 2022). "Donor CYP2B6*6 was associated with Veno-occlusive disease of the liver meanwhile recipient CYP2B6*2 and *4 were associated with hemorrhagic cystitis and oral mucositis correspondingly." (PMID 34322158, 2021). "A study conducted in patients with leukemia who underwent hematopoietic stem cell transplantation showed that carriers of CYP2B6*2A or CYP2B6*4 variant alleles treated with cyclophosphamide were at higher risk of developing hemorrhagic cystitis and oral mucositis, respectively." (PMID 23189085, 2012). "In terms of the coding region, CYP2B6*2 (c.64C > T) and CYP2B6*4 (c.785A > G) mutations increased enzyme activity, which significantly increased the risk of ADR (hemorrhagic cystitis and oral mucositis, respectively) for people with these allele mutations." (PMID 35935867, 2022). "The patients’ CYP2B6 metabolizer phenotypes were associated with the occurrence of lymphopenia, thrombocytopenia, and monocytopenia as well as of liver injury, but not with kidney or urinary bladder (hemorrhagic cystitis) toxicities." (PMID 37479763, 2023).
liver disease (6 papers, 2012 to 2024). "Our study supports the concept in the literature that differences between healthy control VOCs and liver disease patients are linked to CYP450, CYP2E1 enzyme, and CYP2B6 isoform activity alteration in the body due to liver injury." (PMID 37967076, 2023).
virus infection (6 papers, 2016 to 2023). "MRNA expression of HNF3β by virus infection was associated with enhanced expression of CYP2B6 in HepG2 cells in a concentration-dependent manner." (PMID 26930610, 2016).
lung carcinoma (5 papers, 2013 to 2022). "CYP2B6 metabolically activates tobacco-specific nitrosamines, including the procarcinogen 4-(methylnitrosamino)-1-(-3-pyridyl)-1-butanone (NNK), while genetic variations in CYP2B6 have been suggested as a lung cancer risk factor in smokers." (PMID 27738743, 2017). "CYP2B6 gene variants are biologically positioned to influence the risk of developing lung cancer among cigarette smokers through altered enzymatic activation of nitrosamines." (PMID 23591849, 2013). "Based on our findings, lung cancer genetic association studies among ethnic populations with a higher percentage of CYP2B6 gene variants would be beneficial to validate our observations." (PMID 23591849, 2013). "Findings from this pilot point to genetic variation in CYP2B6 as a lung cancer risk factor supporting a role for nitrosamine metabolic activation in the molecular mechanism of lung carcinogenesis." (PMID 23591849, 2013). "Here, we present a feasibility study of genetic variation in CYP2B6 as a potential lung cancer risk factor." (PMID 23591849, 2013). "Furthermore, additional animal studies modulating the expression and/or activity level of nitrosamine metabolizing enzymes, such as CYP2A and CYP2B, would provide valuable insight into the biological mechanism behind our observed differences in lung cancer risk by CYP2B6 and CYP2A6 gene variants." (PMID 23591849, 2013). "Consequently, CYP2B6 gene variants are biologically positioned to influence the risk of developing lung cancer among cigarette smokers through altered metabolic activation of nitrosamines (potentially within the lung) as opposed to indirectly through cigarette consumption." (PMID 23591849, 2013). "We explored the contribution of nitrosamine metabolism to lung cancer in a pilot investigation of genetic variation in CYP2B6, a high-affinity enzymatic activator of tobacco-specific nitrosamines with a negligible role in nicotine metabolism." (PMID 23591849, 2013). "We found evidence that variation in CYP2B6 influences lung cancer risk with a similar magnitude to CYP2A6 and that variation in these genes influences lung cancer risk independently." (PMID 23591849, 2013). "Preferential enzymatic activation of distinct TSNAs, NNK by CYP2B6 and NNN by CYP2A6, may underlie the observed independent contributions of these genes to lung cancer risk." (PMID 23591849, 2013). "Combined analyses of concurrent variation in CYP2B6, CYP2A6 and CHRNA5-A3-B4 appeared to stratify ever-smokers by lung cancer risk supporting an important role for variation in both nicotine/nitrosamine pharmacokinetic and pharmacodynamic pathways to the risk for lung cancer among smokers." (PMID 23591849, 2013).
alcoholism (4 papers, 2013 to 2025). "Furthermore, a protective factor associated with treatment response was the ABCB1 2677T allele and the CYP2B6 785G allele, and the risk factors were HCV infection, alcohol problems, and diagnosis with a psychiatric disease." (PMID 24455721, 2013).
Anxiety (4 papers, 2020 to 2024). Intense feelings of nervousness, tension, or panic often arise in response to interpersonal stresses. "Grouped CNS ADRs (nightmares, insomnia, anxiety, and suicide attempt) also showed a statistically significant association with CYP2B6 c.516G > T in the codominant and recessive models (OR = 30.00, p = 0.011 and OR = 14.99, p = 0.021, respectively)." (PMID 34093191, 2021). "This study also reports that the metabolizer status of CYP2B6 was unable to meaningfully predict improvements in depressive and anxiety symptoms as well as dissociation." (PMID 38477185, 2024). "Univariate logistic regression between CYP2B6 c.516G>T (rs3745274) and CNS toxicity (nightmares, insomnia, anxiety, and suicide attempt grouped) in EFV-treated patients." (PMID 34093191, 2021).
atherosclerosis (4 papers, 2010 to 2025). A disease characterized by the build-up of fatty material and calcium deposition in the arterial wall resulting in partial or complete occlusion of the arterial lumen. "CYP3A4 was involved in all metabolism pathways, and CYP2B6 was linked to lipid metabolism and atherosclerosis." (PMID 41155650, 2025).
colorectal cancer (4 papers, 2007 to 2022). A primary or metastatic malignant neoplasm that affects the colon or rectum. "In T84 cells, which are derived from human colorectal carcinoma and thought to be a potential alternative to Caco-2 cells, the expression of CYP3A4 is controversial, while expressions of CYP2B6, CYP2C9, CYP2C19, and CYP2E1 are lacking." (PMID 34604364, 2021).
glioblastoma (4 papers, 2017 to 2024). The most malignant astrocytic tumor (WHO grade IV). "A study explored using a CYP2B6 gene therapy in combination with neural stem/progenitor cells for treating glioblastoma multiforme (GBM), a highly aggressive brain tumor." (PMID 38860140, 2024).
insomnia (4 papers, 2009 to 2021). A sleep disorder characterized by difficulty in falling asleep and/or remaining asleep. "There was a tendency of CYP2B6*6 genotype association with higher incidence of having vivid dream (p=0.05), insomnia (p=0.19) and tactile hallucination (p=0.09) at week-2." (PMID 23734829, 2013). "The tendency of CYP2B6*6 genotype association with higher incidence of having vivid dream (p=0.05), insomnia (p=0.19) and tactile hallucination (p=0.09) was observed mainly at week-2." (PMID 23734829, 2013). "CYP2B6*6 genotype was associated with vivid dreams (p=0.05), sleepwalking (p=0.11), insomnia (p=0.19) and tactile hallucination (p=0.09)." (PMID 23734829, 2013). "Self-reported treatment-emergent adverse events were captured at each follow-up visit: nausea and vomiting were more common among the CYP2B6 slow metabolizers (5/45; 11.1%), and insomnia was more common among the CYP2B6 extensive metabolizers (5/49; 10.2%) and in the dolutegravir arm (22/342; 6.4%)." (PMID 32960272, 2021).
leukemia (4 papers, 2011 to 2024). A malignant (clonal) hematologic disorder, involving hematopoietic stem cells and characterized by the presence of primitive or atypical myeloid or lymphoid cells in the bone marrow and the blood. "They suggested that the inherited impaired function of the CYP2B6 detoxification pathway may be an essential genetic determinant of leukemia risk." (PMID 38560574, 2024). "Accumulating evidence has provided insights into the substrates, inducers, inhibitors, and gene polymorphisms of CYP2B6; however, potential correlations between CYP2B6 polymorphisms and tumors, especially the occurrence and prognosis of leukemia, remain to be established." (PMID 32119768, 2020).
liver fibrosis (4 papers, 2020 to 2025). "An additional aim was to analyze the association between the degree of liver fibrosis, level of liver inflammation, and potential impact of applied antiviral and antiretroviral therapeutics on the expression of CYP3A4, CYP2B6, and ABCB1 transporters in this patient population." (PMID 37512019, 2023). "The mRNA levels of CYP2B6, CYP3A4, and ABCB1 was quantified and compared between the groups, along with the analysis of liver fibrosis and inflammation levels." (PMID 37512019, 2023).